BRAF (B-Raf proto-oncogene, serine/threonine kinase)
Diseases named in the same sentence as BRAF in open-access papers (continued):
Sharing a sentence is not in itself a finding about the gene and the disease.
melanoma (continued). "The simultaneous inhibition of two targets from the same pathway may increase efficacy and prevent the development of resistance, as reported for the use of BRAF and MEK inhibitors for the treatment of melanoma with BRAF mutations." (PMID 29463565, 2018). "Soluble ligands of the transmembrane receptor NKG2D (sULBP-1, sULBP-2), which affect induction or reactivation of T cell responses, were associated with OS for ICI-treated but not for BRAF inhibitor-treated melanoma patients." (PMID 30002656, 2018). "Currently, detection of BRAF and NRAS mutations in ctDNA has shown significant value in predicting treatment response and outcome in melanoma and the recent inclusion of ctDNA analysis in clinical trials further highlights its imminent implementation in clinical practice." (PMID 29343260, 2018). "However, the first BRAF inhibitor tested in patients with melanoma, sorafenib, showed little efficacy either alone or combined with other conventional chemotherapeutic agents." (PMID 30274263, 2018). "Thus, in addition to the NC1 and NC2 enhancer-mediated regulation of FOXD3, the SOX10/FOXD3 axis discovered in mutant BRAF melanoma cells is likely a new component of the complex regulatory network that controls the development of neural crest." (PMID 29295999, 2018). "To test whether FGF1 affects the sensitivity of melanoma cells to BRAF inhibition, we treated the melanoma cell lines M14, UACC-62, and A375 for 5 days with 2 μM vemurafenib in absence or presence of AZD4547, FGF1 or a combination of both." (PMID 30237393, 2018). "On December 18, 2015, pembrolizumab received an expanded first-line indication to include previously-untreated advanced melanoma regardless of BRAF mutation status following the results of the KEYNOTE-006 trial." (PMID 29357948, 2018). "Indeed the standard-of-care for BRAF-targeting in melanoma has now predominantly shifted from the use of single BRAF inhibitors to use in combination with MEK inhibitors." (PMID 29423085, 2018). "Vemurafenib was only associated with G1‐phase cell cycle arrest in the BRAF‐mutant melanoma cells and not those harboring NRAS mutations." (PMID 29112787, 2018). "However, the combination of dabrafenib and trametinib was only moderately effective in patients with BRAF inhibitor–resistant melanoma." (PMID 30053879, 2018). "Therefore, upregulation of RIP1 in melanoma cells with acquired resistance to BRAF inhibitors is primarily due to increased stability of the protein." (PMID 29880840, 2018). "However, in late stage melanomas, longitudinal assessment of ctDNA levels, including BRAF and NRAS mutations in ctDNA, in melanoma patients receiving immunotherapy was predictive of response." (PMID 29343260, 2018). "Notably, selective BRAF inhibitors, such as Vemurafenib and Dabrafenib, have yielded improved clinical outcomes in melanoma patients compared to conventional chemotherapy." (PMID 29385676, 2018). "We next performed experiments in BRAF inhibitor-resistant melanoma cells." (PMID 29743521, 2018). "Indeed, we identify SOX10 as a novel regulator of FOXD3 in human mutant BRAF melanoma that binds to a conserved regulatory element located 270 bp upstream from the transcription starting site and activates FOXD3 transcription." (PMID 29295999, 2018). "Our data indicate that almost half of BRAF-V600E-mutant melanomas express TNFR2." (PMID 30400822, 2018). "Thus, according to our findings, RIPK3 expression is expected to be induced in most anti-melanoma therapies that employ mutant BRAF-specific inhibitors." (PMID 30157175, 2018).
melanoma (continued). "As functional evidence pointed to AKT and ERK hyper-activation as a strategy melanoma cells evolve to tolerate prolonged BRAF and MEK inhibition, we evaluated total and activated (phosphorylated) forms of AKT and ERK (pAKT and pERK) in untreated and treated spheroids." (PMID 30558661, 2018). "In BRAF mutant melanoma, inhibition of ERK1/2 induces FOXD3 and mediates RAF inhibitor resistance." (PMID 29295999, 2018). "After more than two decades with interferon alfa-2a and 2b (IFN) as the only approved drugs in the adjuvant setting for melanoma, new treatment approaches like immune checkpoint inhibitors and BRAF-MEK inhibitors improve the progression free survival (PFS) and also the overall survival (OS)." (PMID 29899854, 2018). "Mutations in the serine/threonine kinase BRAF are the most common genetic alterations in human melanoma; however, B16F10 murine melanoma cells do not present this mutation." (PMID 29899823, 2018). "However, all these mutants had similar sensitivities to the RAF dimer inhibitor, LY3009120, which are comparable with that of BRAF(V600E) in A101D melanoma cell line." (PMID 29930381, 2018). "FGF1 could limit the inhibitory effect of vemurafenib on melanoma cells, while the simultaneous inhibition of BRAF and FGF receptors increased the anti-tumorigenic effect." (PMID 30237393, 2018). "This potential allows for leflunomide to be used in all melanoma cases, not just for tumors harboring BRAF mutations." (PMID 29423085, 2018). "In vitro data were validated in 26 melanoma patients, of which 14 treated with BRAF inhibitor alone and 12 treated with both BRAF and MEK inhibitors, by ELISA assay and droplet digital PCR for measuring MMP-9 serum levels and circulating-free DNA BRAFV600E mutation, respectively." (PMID 30154717, 2018). "Still to be clarified are the effects of Ole on BRAF human melanoma cells." (PMID 30544808, 2018). "In contrast, Akt levels were decreased in all three BRAF inhibitor-resistant melanoma cells." (PMID 29929490, 2018). "To validate that the BRAF mutant tumors were dependent on an active BRAF signaling pathway, we isolated tumorspheres from two of those tumors and we treated them in vitro with dabrafenib, a specific BRAF inhibitor that is currently in clinical trials for BRAFV600E mutant melanomas." (PMID 29654229, 2018). "Here we show that melanoma cells can release eNAMPT, most likely through a non-classical secretory pathway, and independently of their BRAF mutational status, suggesting that these cells are intrinsically able to secrete this enzyme." (PMID 29721178, 2018). "Hepatocyte growth factor (HGF) secreted by fibroblasts leads to the resistance of BRAF-mutant melanoma to RAF inhibition via activation of the MAPK pathway, the PI3 K/AKT pathway, and the HGF receptor MET, while similar phenomena also appear in colorectal cancer." (PMID 30038550, 2018). "Thus, our work discovers a novel phosphorylation-dependent regulatory mechanism of SOX10 transcription activity and completes an ERK1/2/SOX10/FOXD3/ERBB3 axis that mediates adaptive resistance to RAF inhibitors in mutant BRAF melanoma cells." (PMID 29295999, 2018). "TNFR1/2 expression patterns on BRAF-mutant melanomas were evaluated by multi-color flow cytometry." (PMID 30400822, 2018). "To determine whether vemurafenib and dabrafenib had differential effects upon the growth of BRAF‐ and NRAS‐mutant melanoma cells, we treated 1205Lu (BRAF mutant) and WM1366 cells (NRAS mutant) chronically (>14 days) with each drug and performed cell counts." (PMID 29112787, 2018).
melanoma (continued). "Guided treatments via molecular characterization of solid tumors using biomarkers such as immunohistochemistry (IHC) and genomic sequencing has resulted in better outcomes in subsets of patients, such as those with EGFR (epidermal growth factor receptor) mutant lung cancer and BRAF mutant melanoma." (PMID 29507702, 2018). "The aim of the study was to evaluate any possible correlation between mutations in main growth-controlling genes (BRAF, NRAS, CDKN2A) and copy number variations in frequently amplified candidate genes (MITF, EGFR, CCND1, cMET, and cKIT) during melanoma initiation and progression." (PMID 29492214, 2018). "In the current study, we screened seven human melanoma cells lines representing distinct oncogenic drivers (two BRAF wild type, five BRAF600E and one NRAS mutant) for their basal metabolic phenotype and observed that all of them displayed OCR/ECAR ratio indicative of OXPHOS activity." (PMID 30651927, 2018). "Therefore, our data provided evidence that miR-550a-3-5p acts as a tumor suppressor via YAP inhibition in multiple cancer cells and a novel therapeutic tool for BRAF inhibitor resistance in BRAF-mutant colon and melanoma cells." (PMID 29844307, 2018). "However, in non-V600 BRAF mutant melanoma patients the BRAF V600E selective inhibitors (vemurafenib or dabrafenib) had only disease progression as the best response to therapy." (PMID 29739364, 2018). "In addition, either high MIFT-levels or a low MIFT/AXL-ratio were shown to be associated with resistance of BRAF-and NRAS-mutant melanoma cells towards kinase inhibitors and other targeted therapies." (PMID 29794999, 2018). "In search for the mechanism(s) responsible for downregulation of CYLD in melanoma cells with acquired resistance to BRAF inhibitors, we found that Snail1, which is known to transcriptionally repress the expression of CYLD22, was increased in resistant melanoma cells." (PMID 29880840, 2018). "Finally, selective sequestration of both recombinant and macrophage-derived TNF using INB03 effectively prevented acquisition of resistance to MAPKi by BRAF-V600E mutant melanoma cell lines in vitro." (PMID 30400822, 2018). "Similarly, BRAF inhibitors result in initial dramatic responses in BRAF mutant melanoma and NSCLC, however these tumors also progress on therapy through additional acquired genetic alterations in BRAF and other factors resulting in pathway reactivation." (PMID 29912950, 2018). "The effectiveness of MAPK cascade-targeting therapies to treat patients with BRAF-V600E-mutant melanomas has been limited by a range of resistance mechanisms that may be driven by the tumor necrosis factor (TNF)." (PMID 30400822, 2018). "A previous study using a panel of melanoma-derived PDX models harboring the BRAF V600E variant described increases in both response rate and duration when ribociclib was combined with the selective BRAF inhibitor encorafenib and compared with single agents." (PMID 30443290, 2018). "In conclusion, we propose that the parallel inhibition of FGFR with BRAF/MEK inhibitors might be beneficial for melanoma patients due to the prevention of drug-induced and secretome-mediated resilience." (PMID 30237393, 2018). "Interestingly, different treatments, including BRAF inhibitors (e.g., vemurafenib) as well as cytotoxic agents (e.g., cisplatin), lead to enrichment of slow-cycling, long-lasting melanoma tumor cells that express H3K4-demethylase JARID1B." (PMID 30466474, 2018). "Since BRAF is also mutated in common nevi, its oncogenic activation is supposed to be a necessary but not sufficient condition for melanoma development (being considered as an initiation event in melanocyte transformation)." (PMID 30218391, 2018). "Notably, a positive correlation was also found between SOX10 and FOXD3 in both data sets when analyzing all melanoma genotypes and selectively BRAF mutant melanoma." (PMID 29295999, 2018).
melanoma (continued). "To investigate the effect of BRAF kinase drug resistance on sRNA composition in patient derived melanoma cell lines, we performed differential expression analysis following classification by TEsmall in two biological replicates of parental and BRAF inhibitor resistant cell lines." (PMID 30349559, 2018). "Point mutations of the v-Raf murine sarcoma viral oncogene homolog B (BRAF) gene occur predominantly in melanoma patients, but may also occur in gliomas." (PMID 29621181, 2018). "Given the high frequency of BRAF mutations in melanoma and PLGG, we hypothesized that senescence may develop in PLGG with BRAF alterations." (PMID 30131528, 2018). "Likewise, in BRAF-mutant melanoma, resistance to BRAF inhibitors is mediated by reactivation of MAPK and PI3K-PTEN-AKT pathways." (PMID 29764517, 2018). "A good clinical condition expressed by the ECOG (Eastern Cooperative Oncology Group) performance status (ECOG PS 0) is associated with prolonged OS for patients receiving PD1ab treatment, as well as for patients receiving other melanoma treatments such as BRAF inhibitors." (PMID 30002656, 2018). "In this section, we provide a more in-depth analysis of the four cancer-drug combinations on which most research has been done: Proteasome inhibitors for multiple myeloma, EGFR inhibitors for breast cancer, cisplatin for lung and ovarian cancer, and BRAF inhibitors for melanoma." (PMID 30456204, 2018). "To assess whether acquired drug resistance changes the melanoma transcriptome, we first established cell lines with acquired resistance to small molecule inhibitors of BRAF and MEK." (PMID 30026510, 2018). "Nevertheless, inhibition of p-ERK may re-sensitize the melanoma cells to the treatment of BRAF inhibitors." (PMID 29929490, 2018). "This suggests that neither oncogenic BRAF nor the hyperactivation of PI3K/AKT signaling by PTEN loss is sufficient to initiate melanoma formation alone." (PMID 30053879, 2018). "Interestingly, treatment with BRAF and MEK inhibitors associated with increased frequency of PD-1+ tumor cells in melanoma patients, and PD-1 expression sensitized melanoma to PD-1 blockade in immunodeficient mice." (PMID 30108594, 2018). "In this study, we investigated the metabolic effects of SR4 and niclosamide, two small molecules that were recently identified as mitochondria uncouplers, against treatment naïve wild type, BRAFV600E and NRAS mutant, and BRAF inhibitor (vemurafenib)-resistant melanomas." (PMID 30651927, 2018). "Consistent with BRAF kinase inhibition in vitro, AZ304 potently reduced ERK phosphorylation (p-ERK), with a mean EC50 of 65 nM in the V600E mutant BRAF containing melanoma cell line A375; an EC50 of 60 nM was obtained for the wild type BRAF melanoma cell line SK-MEL-31." (PMID 29755114, 2018). "SK-MEL-2 melanoma cells with wild-type BRAF were used for comparison." (PMID 29929490, 2018). "Dual inhibitor therapies have been successfully tested in malignant melanoma, where combining BRAF inhibitor (BRAFi) treatment with MEK inhibition (MEKi), improved PFS relative to those treated with BRAFi monotherapy and similarly in colorectal cancer adding EGFR inhibitors (EGFRi) to BRAFi." (PMID 30220966, 2018). "The two non-hotspot mutations detected in one NMZL case, L597Q and N581I, were previously found in BRAF V600 wild-type melanoma and their part in oncogenic cell transformation was functionally proven thus further supporting the role of mutant BRAF in NMZL development." (PMID 29556019, 2018). "Mutations of BRAF are frequent enough in our data for melanoma (46% cases with mutation) and thyroid carcinoma (not yet reported by OncoKB, 56% cases with mutation) for further analysis." (PMID 30442178, 2018). "Thus, enhanced LOXL3 expression cooperates with oncogenic alterations such as active BRAF to transform human melanocytes favoring migration and invasion of melanoma cells and supporting melanoma tumorigenicity." (PMID 29229995, 2018).
melanoma (continued). "Indeed, we found that downregulation of CYLD, which is one of the deubiquitinases of RIP1, was responsible for upregulation of RIP1 in melanoma cells with acquired resistance to BRAF inhibitors." (PMID 29880840, 2018). "However, melanoma cells quickly develop resistance to BRAF inhibitors, leading to high relapse rates." (PMID 29929490, 2018). "In this regard, treatment of melanoma cells in vitro with BRAFV600E inhibitors resulted in elevated presentation of melanoma-associated antigens, irrespective of the melanoma BRAF mutation state." (PMID 29983861, 2018). "He had multiple relapsed stage IV BRAF gene mutant malignant melanoma." (PMID 30255823, 2018). "BRAF or BRAF/MAPK inhibitor therapy enhanced anti-tumor immune responses in melanoma patients." (PMID 30135516, 2018). "Recently, a tight interaction between PPP6C-AurkA and MAPK pathways in controlling proliferative activity and apoptosis in melanoma cells has been demonstrated, contributing to increase the levels of tumor heterogeneity and conferring a resistance signature in BRAF- and NRAS-mutated melanomas." (PMID 30218391, 2018). "In light of these observations, we sought to establish whether USP28 expression was inversely correlated with BRAF expression in melanoma patients." (PMID 29880484, 2018). "Recent landmark adjuvant studies have shown dramatic improvement in the relapse free survival of resected stage III melanoma with the use of single agent nivolumab or single agent pembrolizumab or with the use of dual targeted therapy (dabrafenib and trametinib) for BRAF mutant melanoma." (PMID 30352626, 2018). "Investigating the role of the RIPK3 expression regain in cancer resistance and tumor regrowth in patients following BRAF inhibitor therapies (e.g., melanoma) could be of importance to explain this clinically vital phenomenon." (PMID 30157175, 2018). "Therefore, RIP1 is a novel downstream effector of oncogenic activation of the BRAF/MEK/ERK pathway in melanoma." (PMID 29880840, 2018). "In our experience, selected patients with BRAF‐mutated melanoma and without imminent risk of death can be suitably treated with up‐front immunotherapy followed by targeted therapy." (PMID 30214794, 2018). "Indeed, they described a significant increase in melanoma development rate in Tyr::CreERT2; BrafCA/+; Nf1flox/flox mice compared to the BRAF-mutant counterpart." (PMID 29534457, 2018). "Notably, melanoma drug resistance to BRAF inhibitors in BRAF-mutant melanoma can be mediated by mitochondrial adaptive responses." (PMID 29695835, 2018). "Understanding the crosstalk between oncogene signaling, ROS production by p66Shc, and transformation may identify novel targets for treating melanoma and possibly help to overcome the development of resistance to mutant BRAF‐specific kinase inhibitors." (PMID 29624862, 2018). "Melanoma tumors bearing wild-type BRAF are intrinsically resistant to PLX4032 or Dabrafenib." (PMID 30544808, 2018). "To examine the potential effect of RIP1 on the response of melanoma cells to treatment with BRAF/MEK inhibitors, we silenced RIP1 using two individual siRNAs in two BRAFV600E melanoma cell lines (Mel-CV and Mel-RMu) and two wild-type BRAF melanoma cell lines (ME4405 and Mel-RM)." (PMID 29880840, 2018). "Indeed, in combination with anti-PD-1, phenformin enhanced melanoma inhibition in a BRAF V600E/PTEN-null melanoma mouse model." (PMID 30186236, 2018). "We next used a series of different BRAF-resistant melanoma cells." (PMID 29743521, 2018). "Indeed, many groups have used combination treatments with BRAF inhibitors to inhibit resistance in melanoma cells." (PMID 30186236, 2018).